OXR1 (oxidation resistance 1)
Diseases named in the same sentence as OXR1 in open-access papers (continued):
Sharing a sentence is not in itself a finding about the gene and the disease.
Hyperglycemia (1 paper, 2013). An increased concentration of glucose in the blood. "Genetic OXR-1 deletion in mice improves hyperglycemia under high-fat (HF) diet conditions." (PMID 24416020, 2013).
Hypoglycemia (1 paper, 2014). A decreased concentration of glucose in the blood. "The aim of the present study was to investigate the low dose effects of the OxR1 and OxR2 antagonist, SB-649868, on the HPA axis, specifically, its effects on the sympathetic nervous system (SNS) and neuroendocrine responses to hypoglycemia." (PMID 24770625, 2014).
ischemia (1 paper, 2020). A hypoperfusion of the BLOOD through an organ or tissue caused by a PATHOLOGIC CONSTRICTION or obstruction of its BLOOD VESSELS, or an absence of BLOOD CIRCULATION. "When OXR1 expression is repressed by the siRNA, the antagomir was no longer able to provide protection indicating that OXR1 expression is required to reduce brain damage resulting from ischemia." (PMID 33384581, 2020).
ischemic stroke (1 paper, 2024). A stroke disorder caused by obstruction of blood flow to the brain, due to thrombotic (local blood clot formation) or embolic (due to a blood clot or other material traveling from another site) event. "In contrast, in studies of ischemic stroke, OXA significantly improved neurological deficit scores and reduced inflammatory mediators, primarily through inhibition of the OXR1/NF-κB pathway." (PMID 38760784, 2024).
language disorder (1 paper, 2024). A category of disorders characterized by an impairment in the development of an individual's language capabilities, which is in contrast to his/her non-verbal intellect. "The genes SEMA6D, AUT2 and ROBO1, OXR1 and MUC6 were reported as interesting candidate genes because potential pathogenic variants co-segregated with the language disorder in affected relatives of the respective probands." (PMID 38298611, 2024).
melanoma (1 paper, 2023). A malignant, usually aggressive tumor composed of atypical, neoplastic melanocytes. "In our study, the antioxidant response of M14 melanoma cells to CINN-EO was imperfect, as evidenced by the decreases in OXR1 and SOD3 gene expression." (PMID 36982774, 2023).
multiple system atrophy (1 paper, 2026). Multiple system atrophy (MSA) is a neurodegenerative disorder characterized by autonomic failure (cardiovascular and/or urinary), parkinsonism, cerebellar impairment and corticospinal signs with a median survival of 6-9 years. "OXR1 activation preferentially modulated cellular reactions to fibrils derived from multiple system atrophy (MSA) patients, whereas EMC4 ablation broadly reduced pSyn129 across diverse αSyn polymorphs." (PMID 41911287, 2026).
myeloproliferative disease (1 paper, 2019). "In this light, we performed OXR1 silencing in CD34+ cells, which are the target cells of CALR mutation and from whom the myeloproliferative disease originates." (PMID 31332222, 2019).
neuroblastoma (1 paper, 2025). Neuroblastoma (NB) is the most common solid, extracranial childhood tumor. "Using a mouse neuroblastoma cell line, Neuro-2A, immunofluorescence analysis showed Ncoa7 in the perinuclear region, overlapping with GRASP55, but no detectable expression of Oxr1." (PMID 40445757, 2025).
oncocytomas (1 paper, 2017). "Furthermore, in patients with low OXR1 and MST1R methylation level (NPV: 97%), HOXA9 methylation level distinguished oncocytoma from chRCC and pRCC." (PMID 28662726, 2017). "This performance is similar to that of OXR1 and MST1R methylation panel for RCT (98% sensitivity, 100% specificity), although this panel did not perform as well concerning oncocytoma vs RCC in general." (PMID 28662726, 2017).
osteoporosis (1 paper, 2021). A condition of reduced bone mass, with decreased cortical thickness and a decrease in the number and size of the trabeculae of cancellous bone (but normal chemical composition), resulting in increased fracture incidence. "This study highlights a new epigenetic mechanism underlying oxidative stress-mediated osteoblast senescence and senile osteoporosis, as well as the anti-aging and antioxidation effects of miR-29a, DNA methylation inhibitor, and Oxr1 on age-induced osteoblast dysfunction and bone loss." (PMID 34439496, 2021). "miR-29a reversed FoxO3 loss to improve senescence program through targeting Dnmt3b-mediated FoxO3 methylation and increased antioxidant proteins, including Oxr1, to downregulate oxidative stress and DNA methylation, compromising age-induced osteoblast loss and osteoporosis." (PMID 34439496, 2021).
Polydipsia (1 paper, 2015). Excessive thirst manifested by excessive fluid intake. "Two independent reports identified polymorphisms in OXR-1 that link with psychogenic polydipsia." (PMID 25741247, 2015). "However, experimental polydipsia induced with dopamine receptor-2 antagonists (D2R) is enhanced via simultaneous antagonism of OXR-1, suggesting that loss of OX signaling could also promote over-drinking." (PMID 25741247, 2015).
preeclampsia (1 paper, 2021). Preeclampsia is a hypertensive disorder of pregnancy that is characterized by new-onset hypertension with proteinuria presenting after 20 weeks of gestation, and depending on mild or severe forms may initially present with severe headache, visual disturbances, and hyperreflexia. "Thus, whether exosomal miR-200c-3p can downregulate the expression of OXR1 in the CNS and then accelerate the development of cerebral injury in preeclampsia deserves further study." (PMID 34696680, 2021).
pulmonary hypertension (1 paper, 2024). Increased pressure within the pulmonary circulation due to lung or heart disorder. "The study revealed that crocin affected the oxidation resistance 1 (OXR1) signal pathway in rats by regulating SOD, GSH and CAT, and had a protective effect on MCT-induced pulmonary hypertension." (PMID 39759448, 2024).
retinal degeneration (1 paper, 2020). Degeneration of the retina. "OXR1 localizes to the inner portion of the outer segments of the photoreceptors prior to the onset of retinal degeneration." (PMID 33384581, 2020). "The first study demonstrating a role for OXR1 in retinal degeneration used C57bl6/J mice." (PMID 33384581, 2020). "However, by approximately 14 days, OXR1 mRNA and protein levels are reduced in the C57bl6/J mutant mouse to levels below those measured prior to oxygen exposure and retinal degeneration ensues." (PMID 33384581, 2020).
tauopathy (1 paper, 2024). Neurodegenerative disorders involving deposition of abnormal tau protein isoforms (tau proteins) in neurons and glial cells in the brain. "Additionally, overexpression of OXR1 rescued age-related visual decline, neurodegeneration, and transgenically-induced tauopathy in a fly model." (PMID 38212606, 2024). "mtd/OXR1 overexpression rescued age-related visual decline and tauopathy in a fly model." (PMID 38212606, 2024).
neurodegenerative disease (7 papers, 2011 to 2025). A disorder of the central nervous system characterized by gradual and progressive loss of neural tissue and neurologic function. "We next analyzed -omics datasets from humans to learn more about the conserved nature of OXR1 in neurodegenerative diseases." (PMID 38212606, 2024). "In all, our work implicates OXR1 and its network as a key regulators and potential therapeutic targets to slow aging and age-related neurodegenerative diseases across flies and humans." (PMID 38212606, 2024). "We further show that mtd/OXR1 regulates a network of genes that are essential for protection against brain aging and neurodegenerative diseases across flies and humans." (PMID 38212606, 2024). "We further demonstrate that the OXR1 gene network, conserved in flies and humans, is an important target for brain aging and neurodegenerative diseases." (PMID 38212606, 2024). "This review examines the role of OXR1 in oxidative stress resistance and its impact on neurodegenerative diseases." (PMID 33384581, 2020). "Most recent discoveries of the key roles of OXR1 began as investigations into the genetic mechanisms behind specific neurodegenerative diseases." (PMID 33384581, 2020). "Thus, identifying the mechanism of OXR1 will elucidate a valuable target for neurodegenerative diseases and aging." (PMID 38212606, 2024). "In addition to its potential for the treatment of neurodegenerative diseases, OXR1 also shows excellent effects in delaying lupus related renal failure." (PMID 35360206, 2022). "Studies have shown that OXR1 plays an increasing role in neurodegenerative diseases such as oxygen-induced retinopathy, diabetic retinopathy, PD, ischemia-induced neuronal damage, and ALS due to its outstanding ability to reduce oxidative stress and neurodegeneration." (PMID 35360206, 2022). "In addition to its role in protection of brain neurons, OXR1 appears to play a key role in several neurodegenerative diseases of the retina." (PMID 33384581, 2020). "OXR1 gene therapy could treat multiple neurodegenerative diseases, because oxidative stress is a common event that leads to neuronal cell death." (PMID 33384581, 2020). "Thus, restoring or increasing OXR1 function shows promise as a therapeutic for multiple neurodegenerative diseases." (PMID 33384581, 2020). "OXR1 is emerging as a key player in the pathology of neurodegenerative diseases." (PMID 33384581, 2020). "Thus, OXR1 provides a direct protection from neurodegenerative diseases in addition to its role in regulating gene expression." (PMID 33384581, 2020). "Mice lacking Oxr1 display neurodegeneration and we demonstrated that the levels of Oxr1 were critical for neuronal survival under oxidative conditions; our findings suggested that Oxr1 could serve as a neuroprotective factor in neurodegenerative diseases." (PMID 25792726, 2015). "Whether OXR1 plays a role in all of these neurodegenerative diseases remains to be determined." (PMID 33384581, 2020). "Manipulation of OXR1 levels may have therapeutic benefit in neurodegenerative disease." (PMID 25753484, 2015). "Together, these findings suggest that OXR1 plays an important role in regulating FUS and TDP-43 pathology in neurodegenerative disease." (PMID 25792726, 2015). "OXR1 also appears to interact with other proteins that are not directly related to oxidative stress but do play roles in neurodegenerative diseases." (PMID 33384581, 2020). "Oxr1 therefore has much in common with some of the most important antioxidants; proteins such as SOD2 can be lethal when disrupted but neuroprotective when over-expressed in vivo and have therefore been nominated as potential therapeutic targets in neurodegenerative disease." (PMID 22028674, 2011).
neurological diseases (5 papers, 2011 to 2024). "Multi-omic analyses in flies and humans showed that decreased Mtd/OXR1 is associated with aging and neurological diseases." (PMID 38212606, 2024). "The neuropeptide orexin-A (OXA) has been shown to play a protective role against neurological diseases by modulating the inflammatory response through the activation of OXR1 and OXR2 receptors." (PMID 38760784, 2024). "It has been reported that loss of function of OXR1, NCOA7, and TBC1D24 is associated with neurological diseases, including ASD, characterized by aberrant neurodevelopment." (PMID 37958785, 2023). "In addition to studies on OXR1, TBC1D24 is associated with a range of severe human neurological disorders." (PMID 26668325, 2016).
tumor (5 papers, 2017 to 2024). "We pooled all 20 genes (Stx6, Ramp1, Traf3ip1, Nckap5, Pfkfb2, Trmt1l, Rprd1b, Rer1, Sepsecs, Rhobtb1, Tsen15, Abcc3, Arid5b, Tnr, Dock2, Tti1, Fam81a, Oxr1, Plxna2 and Tbc1d31) together as the mouse tumour susceptibility gene signature (mTSGS)." (PMID 39067134, 2024). "Multivariate linear regression analysis identified SNPs in 11 genes (Sepsecs, Rhobtb1, Tsen15, Abcc3, Arid5b, Tnr, Dock2, Tti1, Fam81a, Stx6, and Oxr1) that were independently associated with the tumour multiplicities." (PMID 39067134, 2024). "Tumor samples were categorized as HOXA9 or OXR1 methylated using the respective highest methylation ratio value observed in normal/control samples as cutoff (14.11 for HOXA9 and 1577.45 for OXR1)." (PMID 28662726, 2017). "Both high HOXA9 and OXR1 promoter methylation levels discriminated normal from tumour samples with good sensitivity and high specificity (73 and 89% for HOXA9 and 87 and 100% for OXR1, respectively)." (PMID 28662726, 2017). "Multivariate analyses flagged SNPs in 20 genes (Stx6, Ramp1, Traf3ip1, Nckap5, Pfkfb2, Trmt1l, Rprd1b, Rer1, Sepsecs, Rhobtb1, Tsen15, Abcc3, Arid5b, Tnr, Dock2, Tti1, Fam81a, Oxr1, Plxna2, and Tbc1d31) independently tied to various tumour characteristics, designated as a mTSGS." (PMID 39067134, 2024). "Interestingly, stem-like tumor cells demonstrated overexpression of OXR1 and PON2, both involved in protection against ROS accumulating as co-product of OXPHOS." (PMID 33806447, 2021). "Using these criteria, 73 and 87% of tumor samples were considered hypermethylated at HOXA9 and OXR1 promoters, respectively." (PMID 28662726, 2017). "Further studies are needed to address whether expression of OXR1 and PON2 may be involved in a mechanism by which this long-lived and thus vulnerable population of stem-like tumor cells protects itself against ROS-mediated damage." (PMID 33806447, 2021).
infection (4 papers, 2009 to 2017). The state of being infected such as from the introduction of a foreign agent such as serum, vaccine, antigenic substance or organism. "We have previously shown that OXR1 silencing decreases the number of Plasmodium berghei mature oocysts present six days post-infection (dpi)." (PMID 20567517, 2010). "As it has been observed previously that systemic ROS levels can influence Plasmodium berghei infection, it was hypothesised that the lower rate of infection in A. gambiae following OXR1 silencing was due to the decrease in expression of ROS-clearing enzymes." (PMID 28707022, 2017). "Our study also identified a novel potential function for Oxr1 in the inflammatory response, which is in line with findings from a recent study in Drosophila, which demonstrated that the TLDc domain-containing protein Mustard (Mtd) regulates the innate immune response and tolerance to infection." (PMID 25792726, 2015). "OXR1 silencing decreases Plasmodium infection in the mosquito, while JNK silencing has the opposite effect and enhances infection." (PMID 20567517, 2010). "To better define the stage of the parasite that is affected by OXR1 silencing, we analyzed OXR1 expression in the midgut and carcass (rest of the mosquito without midgut) at early stages of infection, 24 and 28 h hpi." (PMID 20567517, 2010). "For example, OXR1 depletion in A. gambiae does not affect infection with the African Plasmodium falciparum 3D7 strain." (PMID 20567517, 2010).
cancer (3 papers, 2019 to 2024). A tumor composed of atypical neoplastic, often pleomorphic cells that invade other tissues. "A total of 41% of pancreato-biliary ITPNs showed a heterogeneous amplification of that region, which contains different cancer-specific genes (e.g., oxidation resistance 1 OXR1, and the prominent proto-oncogene MYC)." (PMID 34205964, 2021).
OXR1 also shares sentences with these, for which no sentence is quoted: anaemia (1 paper); cardiac arrest (1); Cerebral ischemia (1); dementia (1); epilepsy (1); glomerulonephritis (1); intracerebral hemorrhage (1); kidney failure (1); migraine (1); Neurodegeneration (1); Obesity (1); Parkinson’s (1); sarcoma (1); specific language impairment (1); synucleinopathies (1).